FOXA1 (forkhead box A1)
Diseases named in the same sentence as FOXA1 in open-access papers (continued):
Sharing a sentence is not in itself a finding about the gene and the disease.
breast carcinoma (continued). "We think that under conditions of FoxM1 over-expression there is a gain-of-function for Rb (and Rb family proteins) in which it participates in development/maintenance of poorly differentiated breast cancer cells by inhibiting expression of differentiation genes, such as GATA3 and FoxA1." (PMID 28387346, 2017). "Also, enhanceosome comprising ER, FOXA1, and GATA3 was found to be sufficient to restore estrogen responsiveness in ER− breast cancer cells." (PMID 28345661, 2017). "In contrast, the HB2 cell line is a human mammary epithelial cell line with hardly detectable levels of SPDEF and very low levels of FOXA1 compared with ER+ breast cancer cell lines, whose growth does not depend on SPDEF and FOXA1 activity." (PMID 27997592, 2016). "Similar to NUMB, the EMT negative regulators GATA3 and FOXA1 had significantly lower expression in the BLBC subtypes and in ER-negative and higher histological grade breast cancer patients, whereas the EMT inducers FOXC1, FOXC2 and SNAI1 mimicked the expression profile of Notch1." (PMID 27506933, 2016). "Taken together, these data all support the existence of a subgroup of ERα-positive breast cancers that become endocrine therapy resistant through activation of the EGFR signaling pathway, which may be mediated by a dynamic FOXA1 DNA binding landscape." (PMID 27129152, 2016). "Similar to NUMB, the EMT negative regulators GATA3 and FOXA1 had significantly lower expression in the BLBC subtypes, ER-negative and higher histological grade breast cancer patients, while the EMT inducers FOXC1, FOXC2 and SNAI1 mimicked the expression profiles of Notch1." (PMID 27506933, 2016). "FOXA1 suppresses EMT in pancreatic cancer, prostate cancer and breast cancer." (PMID 27829043, 2016). "In this study, we show that FOXA1 expression is negatively regulated by promoter methylation and silencing, and that BRCA1 regulates FOXA1 expression through suppressing its methylation in both human breast cancer cells and MMECs." (PMID 25531315, 2015). "However, across all 48performing screens, CDK4 and FOXA1 each show BF > 20 in 4 cell lines; two of the four CDK4lines and three of the four FOXA1 lines are HER2+ breast cancer lines, and theremainder are all luminal subtype." (PMID 24987113, 2014). "Well-studied subtype-specific breast cancer oncogenesCDK4 and FOXA1 are not classified as essential in any of the top 12 screens, including HCC-1954,though this line does show a dependence on Her2/ERBB2 (BF = 9.21)." (PMID 24987113, 2014). "We then looked at the lncRNAs near ESR1, GATA3, and FOXA1 and analyzed if their expression is only coordinated in luminal breast cancer but not in basal-like breast cancer as the high expression of these genes is characteristic in luminal breast cancer." (PMID 25296969, 2014). "In fact, the Oncotype DX test for breast cancer prognosis shows a negative and significant correlation between FOXA1 expression and recurrence." (PMID 23192763, 2013). "In addition to ER alpha, we also identified FOXA1 and GATA3 as the TFs with significantly higher activities in ER+ than in ER- breast cancer samples." (PMID 23885756, 2013). "FOXA1 plays a crucial role in developmental ductal morphogenesis in the breast and it has recently been demonstrated that it is a critical mediator of IGF-I effects on breast cancer cell growth and survival." (PMID 23907184, 2013). "FOXA1 and GATA3 proteins are expressed in ER-positive luminal breast cancers." (PMID 23192763, 2013). "FoxA1 does not appear to provide any additional power to discriminate breast cancer subtypes in comparison to ERα profiling." (PMID 22125492, 2011).
breast carcinoma (continued). "To assess the relation between genome-wide binding and expression profiles we cross-examined the estrogen responsive gene lists (all estrogen responsive genes and PBX1-dependent estrogen responsive genes) defined in MCF7 breast cancer cells against the binding profiles for ERα, PBX1 and FoxA1." (PMID 22125492, 2011). "FOXA1, ESR1 and UBE2C, are known as breast cancer prognosis biomarkers." (PMID 21806811, 2011). "GATA-3 was neither a predictor for breast cancer disease-free survival nor a prognostic marker, but was shown to be an important and robust luminal differentiation marker, even stronger than FOXA1." (PMID 19549328, 2009). "In breast cancer, FOG-2 expression is also correlated with favourable prognosis, likely as it is required for the normal expression of its downstream target genes Esr1 and Foxa1." (PMID 19707195, 2009). "Based on this intricate and functional complex between FOXA1 and GATA-3 in breast cancer biology, it is reasonable to consider that these transcription factors, in addition to ERα, are important in establishing and clarifying the hormone-responsive phenotype and prognosis in breast cancer." (PMID 19549328, 2009). "In the present work, we studied FOXA1 and GATA-3 expression in order to evaluate whether the proteins would predict the recurrence behaviour of breast cancer patients." (PMID 19549328, 2009). "In contrast, when FOXA1 is deacetylated by HDAC2, it may bind to chromatin regions that are less likely to be enriched with ER binding, driving transcription independently of ER in breast cancer." (PMID 41224124, 2025). "While GATA3, ESR1, PIK3CA, FOXA1, FOXO3, and RB1 protein abundances were not significantly reduced in GATA3mut breast cancers, the expression of genes associated with MDM2 function and phosphorylation of genes associated with ERK signaling and aggressive phenotypes were impacted." (PMID 40439821, 2025). "However, unlike FOXA1, this indirect down-regulation of ER level, caused by competition between FOXC1 and GATA3, cannot inhibit the progression of breast cancer." (PMID 40003882, 2025). "Additionally, while we identified and validated the relationship between FOXA1 and breast cancer genomic stability and HRD, we did not delve into the underlying mechanisms and associated pathways." (PMID 39440050, 2024). "Additionally, FOXA1 and the SWI/SNF chromatin remodelling complex may be beneficial therapeutic targets in advanced breast cancer." (PMID 39282472, 2024). "However, the expression of FOXA1 and ERα has decreased in TAM-R breast cancer cells, but the activation of transcription factor nuclear factor-κb (NF-κB) and the expression of its target protein IL6 is increased in these cells, contributing to cancer stem cell properties of TAM-R cells." (PMID 38605023, 2024). "Furthermore, in tumor cell invasion experiments using Boyden chambers, the absence of the FOXA1 gene had a significant effect on inhibiting metastasis of breast cancer-positive cell lines but no such effect in TNBC cell lines." (PMID 39000600, 2024). "Therefore, FOXA1, a biomarker with the potential to simultaneously screen for sensitivity to NAC and PARP inhibitors in breast cancer patients, holds significant clinical translational promise for future clinical application, facilitating the development of personalized treatment regimens." (PMID 39440050, 2024). "Also, the FOXA1 KO significantly decreased the tumor cell growth and invasion in hormone-positive (HR+) breast cancer cell lines, MCF-7 and T47D, but not TNBC." (PMID 39000600, 2024). "However, the tumor cell growth inhibition effect caused by FOXA1 gene deletion was not seen in TNBC cell lines, another breast cancer subtype." (PMID 39000600, 2024).
breast carcinoma (continued). "Five of the 14 diabetes-related genes, FOXA1, KIF22, PAK4, MTA3, and FGFR3, were specifically highly expressed in only the ER+/PR+ and ER+/PR− subtypes but not ER−/PR+ and ER−/PR− through an analysis using 4032 patient tissue samples from Breast Cancer Gene Expression Miner v4.5." (PMID 39000600, 2024). "Furthermore, in breast cancer cells, transcription of DSCAM-AS1 was shown to be mainly activated by FOXA1 and was in turn able to affect expression of its regulators ERα and FOXA1 via interaction with YBX1, forming a positive feedback loop leading to breast cancer progression." (PMID 35885035, 2022). "Finally, we validate that FOXA1 and GATA3 mediate hypo-methylated regions in breast cancer cells." (PMID 35331302, 2022). "Indeed, silencing FOXA1 expression in HER2-enriched breast cancer cell lines inhibits proliferation, independent of ER expression." (PMID 34680352, 2021). "Therefore FOXA1 (Hepatocyte nuclear factor 3a; HNF3a), a member of the Forkhead box (Fox) family of transcription factors that reportedly acts as a transcriptional regulator of HER3 in breast cancer cell lines was selected for further study." (PMID 33669586, 2021). "However, FOXA1 is sufficient for ER chromatin occupancy and activation of breast cancer signature genes in non-breast cancer cells that typically have low/undetectable FOXA1 expression (i.e., osteosarcoma cells)." (PMID 34680352, 2021). "However, ER is not the sole nuclear receptor (NR) expressed in breast cancers, nor is it the only NR for which FOXA1 serves as a licensing factor." (PMID 34680352, 2021). "Moreover, FOXA1 can recruit the histone-lysine N-methyltransferase, MLL3, to facilitate the deposition of H3K4me1 histone marks, and as a result, demarcating active enhancer elements in luminal breast cancer cell lines." (PMID 34680352, 2021). "Genetic fine-mapping studies in breast cancer suggest that cis-regulatory risk variants may disrupt DNA binding affinities of TFs, particularly for known master regulators FOXA1 and ESR1, altering the regulation of gene expression and affecting breast cancer risk." (PMID 34518541, 2021). "Previously, we showed that estrogen receptor and FOXA1, which are known to be activated in estrogen receptor-positive breast cancer subtypes (e.g. luminal A, luminal B), are not expressed in the basal subtype, but FOX and MYB motifs are enriched at enhancers in basal-like breast cancer cells." (PMID 32925947, 2020). "Interestingly, in breast cancer, estrogen receptor‐bound SEs are also bound by MED1 and FOXA1, which act as facilitators for the interaction with neighboring enhancers, and lists of highly active SEs which potentially play a critical role in this tumor type have just been reported." (PMID 32333502, 2020). "Based on our results, we conclude that the expression level of FOXA1 is significantly higher in breast cancer than in noncancerous tissues, and the effects of FOXA1 could be mediated by the ESR1 pathway." (PMID 31562808, 2019). "Difficulty in handling and manipulation of an in vitro study could not find out details of subcellular molecular mechanisms between AR and FOXA1 and many other ER-positive, luminal subtype breast cancer cell lines were not investigated." (PMID 29137314, 2017). "The roles of changes in the AR or FOXA1 genes have not been much studied in female breast cancers." (PMID 29137314, 2017). "This occured despite the importance of FOXA1 in process involved in cancer development: it forms a strong network with ER- α (estrogen receptor-alpha) and GATA-3 (GATA binding protein 3) and controls the gene expression pattern in luminal subtype A breast cancers." (PMID 26537518, 2015). "Increasing numbers of genes involved in breast cancer have been found, including Ets-1 (E-twenty-six-1), PKC (protein kinase C), CEP4 (CDC42 effector protein 4), Her2 (erb-b2 receptor tyrosine kinase 2), ALDH1 (aldehyde dehydrogenase 2), FOXA1 (forkhead box A1) and HOXD10 (homeobox D10)." (PMID 25739083, 2015).
breast carcinoma (continued). "Since the GDS3283 is a breast cancer data set, we selected the ChIP-seq experiments from breast cancer cell lines (T47D and MCF7 cells) to generate the regulatory TF network with Q < 0.001, which contained five significant TFs: ESR1, GATA3, FOXA1, MYC and E2F1." (PMID 24302579, 2014). "It is worthy to note that also the pioneer factor FoxA1 recruits ERα to H3K4me2-enriched regulatory elements in breast cancer cells, but only PBX1 expression correlated with metastasis formation and development of resistance to endocrine therapies in patients with ERα positive breast cancer." (PMID 25436603, 2012). "Importantly, PBX1 depletion in MCF7 breast cancer cells did not affect ERα or FoxA1 expression both at the mRNA and protein level." (PMID 22125492, 2011). "As FOXA1 may also be a downstream effector of GATA-3, it may be a bridge between GATA-3 and ER pathways, controlling and regulating the biology of luminal mammary cells, breast cancer progression and behaviour." (PMID 19549328, 2009). "As there was an increased expression of the FOXA1 gene expression was more in the HR+ breast cancer subtype than other diabetes-related genes, we focused on whether or not FOXA1 would affect the breast cancer patient survival rate using the Kaplan–Meier plotter." (PMID 39000600, 2024). "Given that of all the breast cancer models investigated, the MDA-MB-453 cell line is the only one in which AR signaling can promote rather than inhibit proliferation, increased or preferential interaction with FOXA1 over GATA3 or other factors may underpin this distinct biology." (PMID 38317241, 2024). "In our in vitro experiment, we observed FOXA1 expression exclusively in the three hormone-receptor-positive breast cancer (HR+ BC) cell lines, with no detection in the triple-negative breast cancer (TNBC) cell lines." (PMID 39000600, 2024). "When the hormone-receptor-positive breast cancer (HR+ BC) cells were treated with metformin, the cancer cell group with FOXA1 KO did not affect cell growth, indicating that FOXA1 is regulated by metformin." (PMID 39000600, 2024). "This suggested that FOXA1 might be one negative TF for HTR6 in breast cancer." (PMID 35359970, 2022). "Thus, together with other TFs such as Forkhead box protein A1 (FoxA1) and Activating enhancer binding Protein 2 γ (AP-2γ), the estrogen-independent activity of ERα seems important in maintaining the luminal epithelial phenotype and blocking EMT in breast cancer cells." (PMID 26621851, 2016). "While the relationship between FOXA1 and EMT genes has been explored in prostate and breast cancers, its role in liver cancer resistance has not been deeply studied before." (PMID 40216647, 2025). "Together, these studies indicate that enhancers occupied by ER⍺, FOXA1, and GATA3 frequently also bind GRHL2, but a majority of conserved GRHL2 binding sites in luminal breast cancer cells do not overlap with binding of the ER⍺ signaling complex." (PMID 36691073, 2023). "The FOXA1 gene, which opposes SOX10 expression, cooperates with ER1 to maintain luminal identity in breast cancer, whereas GATA3, XBP1, and CA12 showing a negative correlation with SOX10, also cooperate in ER1 signaling." (PMID 36496864, 2022). "Independent of CREB5 and FOXA1, TBX3 expression has been shown to be required for viability of breast cancer cells." (PMID 35550030, 2022). "FOXA1, together with EP300 and RUNX1, regulates the expression of E-cadherin, and is expressed in luminal, but absent in triple-negative and basal-like breast cancers." (PMID 33417085, 2021). "Moreover, there were higher observed co-expression scores for FOXM1/E2F1, FOXA1/GRHL2, FOXA1/GATA3, suggesting that absence of FOXA1 might contribute to doxorubicin resistance in breast cancer cells through collaboration with the down-regulated GRHL2 and/or GATA3." (PMID 34395436, 2021). "Unlike FOXA1, expression of FOXC1 correlates with the basal-like breast cancer subtype and predicts poor breast cancer patients outcome." (PMID 29864144, 2018).
breast carcinoma (continued). "Recruitment to chromatin was shown to be dependent of FOXA1 in breast cancer cells, however in an osteoblast like cell line (U2OS-ERα) FOXA1 is not expressed and ERα binding is independent of FOXA1." (PMID 24849812, 2014). "For example, binding motifs for E2F and Fox family members, including FOXO1 (FOXO1A), FOXA1 (HNF3A), and FOXF2 (FREAC2,4), are highly enriched in PR-binding sites in breast cancer cells but not in leiomyoma cells." (PMID 22272226, 2012). "In breast cancer alone, up to 50% of patients with Rbness in the absence of RB1 genomic alterations harbored amplifications in PIK3CA, RB (CCND1 and CCNE1), and ER signaling modules (ESR1, FOXA1, and GATA3)." (PMID 40138429, 2025). "While general tumor spheroid formation occurred in the control sgRNA, the cancer spheroid formation could not be as well detected in the two different FOXA1 deletion groups for hormone-receptor-positive breast cancer (HR+ BC), such as MCF-7 and T47D cell lines." (PMID 39000600, 2024). "As expected, prostate and breast cancer cell lines exhibited the highest degree of FOXA1 dependence, but a cohort of NSCLC cell lines also demonstrated reduced cellular fitness (negative “gene effect” value) following FOXA1 knockout." (PMID 37691854, 2023). "The significance of these findings was not confined to breast cancer patients, since overall survival (OS) in HER2-positive gastric cancer patients was also significantly lower if patients expressed high combined mean mRNA levels of JAM-A, HER2 and FOXA1." (PMID 35203384, 2022). "Similarly, some other eRGs such as FOXA1 and ERBB2, were also found to be differentially expressed in basal vs. non-basal breast cancer samples probably owing to the differential enhancer methylation." (PMID 28621677, 2017). "The purpose of this study was to explore if the expression of FOXA1 and GATA-3 may provide an opportunity to stratify subsets of patients that could have better outcome, among the ERα-negative/poor prognosis breast cancer group." (PMID 19549328, 2009). "Moreover, intersection of our identified GRHL2 peaks with published ER⍺ binding events in the same series of luminal breast cancer cells cultured under the same conditions further indicates that GRHL2 binds most of the targets found by us in absence of ER⍺, FOXA1, and GATA3." (PMID 36691073, 2023). "In the BRCA samples of TCGA, we also noticed a significant relationship between AGR2 expression and FOXA1 gene copy number, as well as several cancer gene copy numbers localized at 14q such as NFKBIA, SAV1, CHD8 or AJUBA, which are not known as driver oncogenes or TSG in breast cancer." (PMID 35857928, 2022). "Furthermore, while ESR1 can initially upregulate AGR2 expression, breast cancer cells that achieve tamoxifen resistance no longer require ESR1 for AGR2 expression, likely due to an alteration in the activity of the transcription factor FOXA1." (PMID 29796176, 2018). "Importantly, FOXA1, ATF2, ATF3 and many other known key regulators in breast cancer could not be incorporated by any NCA algorithm because of the necessary conditions." (PMID 26537518, 2015).